EEF2 (eukaryotic translation elongation factor 2)
Description:
Catalyzes the GTP-dependent ribosomal translocation step during translation elongation. During this step, the ribosome changes from the pre-translocational (PRE) to the post-translocational (POST) state as the newly formed A-site-bound peptidyl-tRNA and P-site-bound deacylated tRNA move to the P and E sites, respectively. Catalyzes the coordinated movement of the two tRNA molecules, the mRNA and conformational changes in the ribosome.
Synonyms: EF-2; EF2; EEF-2; SCA26
Tractability: Small molecule: a structure with a bound ligand is known. Antibody: its Gene Ontology location is reachable by antibodies, with high confidence. PROTAC: UniProt records ubiquitination sites on it; ubiquitination databases record sites on it; its protein half-life has been measured. Other modalities: an approved drug acts on it.
Target class: Other cytosolic protein
Gene: Protein-coding gene on chromosome 19 (3,976,044 to 3,985,479, reverse strand). Ensembl gene ENSG00000167658.
Subcellular location: Cytoplasm; Nucleus
Subcellular location (Human Protein Atlas): Cytosol; Plasma membrane
Pathways (Reactome):
Metabolism of proteins: Peptide chain elongation; Protein methylation; Synthesis of diphthamide-EEF2
Disease: Uptake and function of diphtheria toxin
Immune System: Neutrophil degranulation
Gene Ontology:
Molecular function: cadherin binding; GTPase activity; protein binding; protein kinase binding; ribosome binding; RNA binding; translation elongation factor activity; 5S rRNA binding; actin filament binding; GTP binding; lncRNA binding
Biological process: positive regulation of translation; translational elongation; cellular response to brain-derived neurotrophic factor stimulus; glial cell proliferation; positive regulation of cytoplasmic translation; response to endoplasmic reticulum stress; response to estradiol; response to ethanol; response to folic acid; response to hydrogen peroxide; response to ischemia; response to xenobiotic stimulus; skeletal muscle cell differentiation; skeletal muscle contraction; translation; translation at postsynapse
Cellular component: cytoplasm; cytosol; extracellular exosome; membrane; nucleus; ribonucleoprotein complex; extracellular region; ficolin-1-rich granule lumen; secretory granule lumen; glutamatergic synapse; postsynapse; ribosome; synapse
Genetic constraint (gnomAD): Loss-of-function variants: 20 observed, 74.61 expected, observed/expected ratio (o/e) 0.27, 90% interval 0.19 to 0.39. The synonymous counts are far from expectation, so gnomAD's model fits this gene poorly and the ratio says little. Missense variants: 805 observed, 1,138.1 expected, observed/expected ratio (o/e) 0.71, 90% interval 0.67 to 0.75. Synonymous variants: 697 observed, 480.53 expected, observed/expected ratio (o/e) 1.45, 90% interval 1.36 to 1.54.
Homologues: Orthologues: chimpanzee EEF2 (100% identical), macaque EEF2 (99% identical), dog EEF2 (99% identical), pig EEF2 (99% identical), rat Eef2 (99% identical), mouse Eef2 (99% identical), tropical clawed frog eef2 (96% identical), guinea pig EEF2 (94% identical), zebrafish eef2l2 (93% identical), Caenorhabditis elegans eef-2 (79% identical), Drosophila melanogaster eEF2 (79% identical). Paralogues in human: EFL1 (38% identical), EFTUD2 (38% identical), GFM1 (21% identical), GFM2 (19% identical), GUF1 (16% identical), EEF1A1 (13% identical), EEF1A2 (13% identical), MTIF2 (12% identical), HBS1L (10% identical), EEFSEC (10% identical), GSPT1 (10% identical), GSPT2 (10% identical), and 6 more.
Diseases named in the same sentence as EEF2 in open-access papers:
EEF2 is named in the same sentence as 128 diseases in open-access papers, as found by Europe PMC text mining. Sharing a sentence is not in itself a finding about the gene and the disease. The quoted sentences say what the papers report.
breast cancer (19 papers, 2013 to 2026). A primary or metastatic malignant neoplasm involving the breast. "Overexpression and amplification of EEF2 protein have been reported in various types of human cancers, including breast cancer and leukemia." (PMID 37958330, 2023). "We showed that eEF2 was overexpressed in the majority of various types of tumors such as lung, esophageal, pancreatic, and breast cancer and promoted growth of various types of cancer cells." (PMID 24589652, 2014). "eEF2 protein was immunohistochemically examined in 51 lung cancers, 15 esophageal squamous cell carcinomas, 21 HNSCCs, 28 pancreatic cancers, 8 breast cancers, 16 glioblastoma multiformes, 4 prostate cancers and 50 NHLs." (PMID 24589652, 2014). "The differences in hazard ratios and log-rank p-values across different patient subgroups suggest that the impact of eEF2 K on survival may vary depending on the specific breast cancer subtype and other clinical factors." (PMID 40266550, 2026). "In cancer biology, eEF2 modification plays a crucial role, as demonstrated by studies using diphthamide-deficient MCF7 breast cancer cells, where the loss of diphthamide blocked ADP-ribosylation, conferring resistance to Pseudomonas exotoxin A (PE) and diphtheria toxin (DT)." (PMID 39707196, 2024). "Besides eEF2 and eEF2 kinase were found to be possible drug targets in gastrointestinal and breast cancer." (PMID 28060762, 2017). "Our findings indicate that PI3Kγ may promote breast cancer metastasis through a novel mechanism, by deactivating eEF2 after IGF-1R-CXCR4 transactivation." (PMID 23320409, 2013). "Kaplan–Meier analysis was performed to evaluate the prognostic significance of eEF2 K expression in triple-negative breast cancer (TNBC) and basal-like breast cancer subtypes." (PMID 40266550, 2026). "The EEF2 protein is inactivated by phosphorylation, and inactivation of EF2K is increased by mTOR activity in breast cancer cells." (PMID 25693800, 2015). "Similarly, for patients with basal-like breast cancer (PAM50 subtype), high eEF2 K expression correlated with reduced OS (HR = 1.84, log-rank p = 0.02), further emphasizing the negative impact of eEF2 K on patient prognosis." (PMID 40266550, 2026). "Therefore, PP2A and phosphorylation status of eEF2 contributed to the acquired resistance of trastuzumab and lapatinib targeted therapy in HER2 overexpressed breast cancer." (PMID 39707196, 2024). "The current literature supports the notion that EEF2 is an OG in human breast cancer due to gene duplication and overexpression rather than point mutations and short indels." (PMID 37958330, 2023). "However, we found underexpression of EEF2 and GLRX2 proteins involved in ROS; MTX2 in MMO; USP30 in MIT; TSPO in MIT and PPM processes; BAX in FUS; and MTFR1L and MIEF1 in FIS compared to luminal A and basal-like breast cancer tumors." (PMID 35327574, 2022). "Our data suggests that decreased eEF2 phosphorylation, mediated by increased PP2A activity, contributes to resistance to HER2 inhibition and may provide novel targets for therapeutic intervention in HER2 positive breast cancer which is resistant to HER2 targeted therapies." (PMID 24958351, 2014).
lung carcinoma (12 papers, 2014 to 2024). "EEF2 was found to be a novel tumor-associated biomarker that is overexpressed in various cancer types, including lung cancer." (PMID 35512017, 2022). "Overexpression of EEF2 correlates with cancer cell growth, metastasis invasion, and poor prognosis in acute myeloid leukemia, breast, and lung cancer." (PMID 34229299, 2021). "Recent studies have demonstrated that EEF2 inhibited lung cancer cell proliferation, and miR-183-5p, a potential prognostic biomarker, regulates cell functions by modulating EEF2 in gastric cancer." (PMID 34790823, 2021). "The eukaryotic translation elongation factors EEF1B2 and EEF2 are down-regulated in breast, esophageal, and lung cancers while EEF1B2 is found with repression in some other cancer types, such as head and neck, leukemia, and pancreatic cancer." (PMID 31242667, 2019). "Overexpression of most factors predicted a poor prognosis in breast (EEF1D, EEF1E1, and EEF2) and lung cancer (EEF1A2, EEF1B2, EEF1G, EEF1E1) in KM analysis." (PMID 29342219, 2018). "Overexpression of many factors predicted poor prognosis in breast (EEF1D, EEF1E1, EEF2) and lung cancer (EEF1A2, EEF1B2, EEF1G, EEF1E1)." (PMID 29342219, 2018). "The contrary functions of EEF2 and LRP1 in lung cancer, along with DST shared expression with EEF2, are evident." (PMID 38389572, 2024). "PRMT7 overexpression also promoted the invasion and colony formation in lung cancer, and the authors of this study found that PRMT7 interacted with mitochondria localized HSP70 family member HSPA5 and elongation factor 2 EEF2." (PMID 34440512, 2021). "Knockdown of eEF2 by short hairpin RNA (shRNA) significantly inhibited the growth in four eEF2-expressing cell lines, PC14 lung cancer, PCI6 pancreatic cancer, HT1080 fibrosarcoma and A172 glioblastoma cells, but not in eEF2-undetectable MCF7 cells." (PMID 24589652, 2014).
depression (10 papers, 2017 to 2025). "Since Gfap and PSD-95 levels are often reduced in depression, and mTOR/EEF2 pathways are implicated in psychiatric disorders, these data further support lurasidone’s neuroprotective profile." (PMID 40141736, 2025). "Additionally, exifone-induced alterations in mTOR/Akt/PI3k signaling and eEF2 activity further supported HDAC1 in the synaptogenesis associated with neuroinflammation-induced depression." (PMID 33526073, 2021). "NH125 treatment reduced the phosphorylation levels of eEF2 and mTOR, while enhanced BDNF and eventually SNAP25 and PSD95 expression, suggesting an etiological role of eEF2 in LPS-induced synaptogenetic dysfunction and depression." (PMID 33526073, 2021). "We investigated the involvement of HDAC1 and eEF2 in the antidepressant mechanisms of fluoxetine using a lipopolysaccharide (LPS)-induced depression-like behavior model." (PMID 33526073, 2021). "Moreover, in de-ovulated model mice, the detection of CREB and eukaryotic translation elongation factor 2 (eEF2) suggested that Ber (10 mg/kg) can improve depression through the BDNF/CREB/eEF2 pathway, and the onset of action is 2–4 weeks faster than SSRI." (PMID 38318145, 2024). "Both pathways inhibit eEF2K activity by phosphorylation of eEF2K on e366, resulting in dephosphorization of eEF2 Thr56, suggesting that eEF2 may be a promising therapeutic target for the treatment of depression." (PMID 36059987, 2022). "Similarly, as a key player in protein synthesis and possibly the core of depression, eEF2 activity and expression were then examined." (PMID 33526073, 2021). "Mice treated with LPS displayed depression-like behaviors, pronounced neuroinflammation, increased HDAC1 expression, and reduced eEF2 activity, as accompanied by altered synaptogenic factors including BDNF, SNAP25, and PSD95." (PMID 33526073, 2021). "Thus, enhancing eEF2 activity by antidepressants might be a crucial strategy against depression." (PMID 33526073, 2021).
colorectal cancer (9 papers, 2013 to 2024). A primary or metastatic malignant neoplasm that affects the colon or rectum. "SurvExpress analysis revealed significantly reduced mRNA levels of EEF1A1, EEF1B2, EEF1E1, EEF1G and EEF2 in the high-risk group, in colorectal cancer and, predicted poor survival." (PMID 29342219, 2018). "Our results therefore warrant further evaluation of anti-phospho-Thr56 eEF2 aAb as a potential diagnostic and possibly prognostic biomarker of colorectal cancer using large cohorts of patients at different stages of the disease." (PMID 24130777, 2013). "Similarly, in colorectal cancer, mutations, such as Rpl24Bst, increase eEF2 phosphorylation, suppressing protein synthesis and tumor growth, which emphasizes eEF2’s role in cancer cell proliferation." (PMID 39707196, 2024). "Finally, RPL24, which we found elevated across our analyses, is known to enhance translation and promote tumorigenesis; its functional inactivation through mutation suppressed colorectal cancer by promoting eEF2 phosphorylation via eEF2K." (PMID 37888706, 2023). "Blood screening for the presence of biomarkers such as anti-phospho-Thr56 eEF2 aAb could contribute to the stratification of patients in risk groups for tailored colorectal cancer prevention programs." (PMID 24130777, 2013). "eEF2 also contributes to chemotherapy resistance, as seen in oxaliplatin-resistant colorectal cancer." (PMID 39707196, 2024). "Expression of RPL24, EEF2K, and EEF2 is consistent with increased eEF2 activity in colorectal cancer (CRC) tumours." (PMID 34895463, 2021). "The frequency of eEF2 overexpression exceeded 70% in lung, esophageal, breast and prostate cancers, and 90% in gastric and colorectal cancers and NHL, as shown in the present and previous studies." (PMID 24589652, 2014). "We further documented that the detection of these aAb preceded the detection of a palpable tumor mass in mice and validated the presence of anti-phospho-Thr56 eEF2 aAb in the serum of patients with adenomatous polyps and colorectal carcinoma." (PMID 24130777, 2013). "Also, we have demonstrated that eEF2 was overexpressed in the majority of gastric and colorectal cancers and promoted progression of G2/M in the cell cycle, resulting in the enhancement of in vitro and in vivo cancer cell growth." (PMID 24589652, 2014). "Previously, we showed that eEF2 was overexpressed in the majority of gastric and colorectal cancers and promoted progression of G2/M of the cell cycle in association with activation of Akt and a G2/M regulator, cdc2 proteins, resulting in the enhancement of in vitro and in vivo cancer cell growth." (PMID 24589652, 2014). "Oncomine analysis of colorectal cancer with the pre-specified thresholds didn’t return any datasets with significant difference in mRNA levels, for EEF1A1, EEF1A2, EEF1B2, EEF1G and EEF2." (PMID 29342219, 2018). "Furthermore, the identification of phospho-eEF2 as an immunogenic entity giving rise to the production of autoantibodies in patients with adenomatous polyps and colorectal cancers indicates that valid post-translational modifications may also be recapitulated with this strategy." (PMID 24130777, 2013). "Similarly, in colorectal cancer (CRC), increased eEF2 phosphorylation, as demonstrated in Rpl24Bst mutant mice, significantly limits tumorigenesis, positioning translation elongation as a key therapeutic target." (PMID 39707196, 2024). "Recently, it has been reported that the eEF2 protein is highly expressed in human breast, lung, gastric and colorectal carcinoma tissues, but not in normal tissues." (PMID 30916466, 2019).
diphtheria (8 papers, 2010 to 2025). A Gram-positive bacterial infection caused by Corynebacterium diphtheriae. "This modification has been extensively studied because it is targeted by the diphtheria toxin which is a potent exotoxin produced by Corynebacterium diphtheriae leading to the ADP-ribosylation of the eEF2 protein at the diphthamide residue causing diphtheria and upper respiratory tract infection." (PMID 40082762, 2025).
cardiac hypertrophy (7 papers, 2013 to 2025). "Decreased eEF2 phosphorylation can be detected within 30 min after angiotensin II treatment in isolated neonatal CMs, together with increased protein synthesis, which is believed to be one of the primary causes of cardiac hypertrophy." (PMID 40869184, 2025). "eEF2 protein, upregulated during cardiac pathological remodeling, enhances global protein synthesis and promotes cardiac hypertrophy." (PMID 40869184, 2025). "In contrast, activating the mTOR pathway reduces Eef2 phosphorylation by inhibiting EF2K, and previous research has shown Eef2 to be upregulated during cardiac hypertrophy." (PMID 37378715, 2023). "We discovered that eucaryotic elongation factor 2 (Eef2) mRNA is bound to Ybx1, and its translation is upregulated during cardiac hypertrophy dependent on Ybx1 expression." (PMID 37378715, 2023). "Our work now further connects translationally controlled Eef2 expression with the regulation of protein synthesis, which is required for pathological cardiac hypertrophy." (PMID 37378715, 2023). "We next examined AMPK downstream targets previously proposed to be involved in the context of cardiac hypertrophy and we first analyzed p70S6K and eEF2, which are involved in the regulation of protein synthesis." (PMID 29371602, 2018). "Furthermore, the inhibition of cell growth could be impacted via the AMPK/eEF2 kinase/eEF2 signaling pathway and slow the progression of cardiac hypertrophy." (PMID 28427148, 2017).
hepatocellular carcinoma (7 papers, 2017 to 2025). A malignant tumor that arises from hepatocytes. "Alkaloids in Coptidis rhizome suppresses eEF2 activity, and then inhibits tumor growth and angiogenesis in animal experiments, suggesting anti-hepatoma efficacy." (PMID 37740172, 2023). "To validate our result, we tested the impact of the depletion of eEF2 and eEF1A on linear invadosomes in hepatoma HuH6 cells." (PMID 29795195, 2018). "eEF2 and phosphorylated eEF2 are prognostic markers for survival of hepatocellular carcinoma patients and the regulating eEF2 kinase is a potential drug target for tumor therapy." (PMID 28060762, 2017). "Moreover, in hepatocellular carcinoma (HCC), eEF2 enhances translation of HMGB2 mRNA, promoting tumor growth and metastasis." (PMID 39707196, 2024). "Expression and distribution of the candidate protein eEF2 and its phosphorylated isoform was validated immunohistochemically on 78 hepatocellular carcinoma and non-tumorous tissue samples." (PMID 28060762, 2017). "Eukaryotic translation elongation factor 2 (EEF2) was found to be overexpressed at the protein level, in gastrointestinal cancers and in hepatocellular carcinoma (HCC)." (PMID 29342219, 2018). "In hepatocellular carcinoma (HCC) studies, Coptis extract containing 4.4% palmatine specifically blocks de novo vascular endothelial growth factor (VEGF) protein synthesis by increasing phosphorylation of eukaryotic elongation factor 2 (eEF2) in HCC cells, thereby exerting anti-angiogenic effects." (PMID 40786032, 2025).
colon cancer (6 papers, 2014 to 2024). "It has been reported that eEF2-derived immunogenic peptide was able to further enhance its capacity of inducing antigen-specific cytotoxic T lymphocytes (CTLs) against colon cancer cells." (PMID 32241270, 2020). "Interestingly, eEF2 was identified as a tumor-associated antigen, and eEF2-derived polypeptides are immunogenic and induce activated CD8+ T cells or cytotoxic T lymphocytes in vitro, suggesting potential adoptive transfer cancer immunotherapeutic for colon cancer." (PMID 39409166, 2024). "Although eEF1A is a phosphorylation target by several kinases, including p70S6 kinase and eEF2 upregulation has been described for ovarian, gastric, and colon cancers, their role in NSCLC has not been addressed adequately." (PMID 33092114, 2020).
malaria (6 papers, 2017 to 2023). Malaria is a serious and sometimes fatal disease caused by a parasite that commonly infects a certain type of mosquito which feeds on humans. "In this respect, eEF2 inhibitor DDD107498 is a more attractive development candidate for reducing malaria transmission as its mode of inhibition of transmission depends on a gametocytocidal activity, combined with a weaker sporontocidal action." (PMID 29247222, 2017). "Clinically validated malaria targets include the targets of licensed drugs cytochrome B (CytB), dihydropteroate synthase (DHPS), DHFR-TS and haeme as well as newer targets such as ATPase4 (ATP4), elongation factor 2 (eEF2), prolyl tRNA synthetase (PRS) and PI4K." (PMID 37652975, 2023).